GCG (glucagon)
Diseases named in the same sentence as GCG in open-access papers (continued):
Sharing a sentence is not in itself a finding about the gene and the disease.
diabetes (continued). "The intra-islet role of the delta-cells and the impact of dysregulated somatostatin secretion on the defective counter-regulatory alpha-cell glucagon response to hypoglycaemia in T1D are excellent examples of a potentially novel tool in diabetes control." (PMID 38612880, 2024). "Given the probable close relationship between glucagon and the metabolic alterations in MASLD, the degree of liver fat is likely to indicate the risk of developing cardiometabolic conditions, including diabetes." (PMID 38705923, 2024). "Diabetes mellitus (DM) is characterized by hyperglycemia resulting from insulin resistance, inadequate insulin secretion, or excessive glucagon secretion." (PMID 38255714, 2024). "Multiple linear regression analysis further showed that the peak C-peptide along with peak glucose affected the iAUC 30-180 glucagon after adjusted for sex, age, BMI, duration of diabetes, and daily insulin dose (R2 = 0·335, P = 0·033)." (PMID 39149119, 2024). "The Cp+/SST+ and GCG+/SST + bi-hormonal cells were reported in zebrafish models of diabetes, lineage tracing experiments in mice, and during beta cell differentiation from human stem cells." (PMID 38933536, 2024). "Its mechanism of action involves stimulating insulin secretion, inhibiting glucagon secretion, slowing gastric emptying, and reducing food intake, making it a valuable tool in diabetes and obesity management." (PMID 38911363, 2024). "It is known that increased glucagon secretion predicts the worsening of glucose tolerance, and paradoxical glucagon hypersecretion and hyperglycemia were seen in diabetes (Honzawa, Fujimoto, and Kitamura 2019)." (PMID 39474783, 2024). "In this study, we investigated the modifications in hypothalamic gene and protein expression induced by repeated bouts of hypoglycaemia in a mouse model of diabetes with defective glucagon secretion." (PMID 38017352, 2024). "First, in patients with diabetes suffering from severe hypoglycemic events the administration of glucagon is an important therapeutic option." (PMID 38681771, 2024). "Due to the reduction in β-cell mass in diabetes, the paracrine regulation by β-cells on glucagon secretion from pancreatic α-cells is defective, leading to hyperglucagonemia." (PMID 39337311, 2024). "Insulin and C-peptide levels were decreased, and the glucose-induced suppression of glucagon was impaired in both diabetes groups (all p < 0.0001 versus." (PMID 39596226, 2024). "The questionnaire was administered to 230 SNs focusing on their general knowledge of diabetes, insulin and glucagon, IP, diabetes complications, nutrition, physical activity, stress, comorbidities, and blood glucose measurements." (PMID 39195172, 2024). "In the normal control rats, glucagon-positive α-cells were localized peripherally in the islet, while in diabetes-induced rats, glucagon-positive α-cells were abundantly found in the central as well as peripheral regions of the islet." (PMID 39337311, 2024). "Acutely, the insulin secretory properties of AA can improve glycaemic control in patients with diabetes, while its effect on glucagon secretion has the potency to impair glucose regulation and is associated with insulin resistance." (PMID 39114126, 2024). "The use of SSTR2a’s to restore glucagon counter regulation in diabetes has been recently reviewed by Hoffman and colleagues." (PMID 38612880, 2024). "Linagliptin is a class drug for the treatment of type 2 diabetes mellitus that can promote the release of insulin from pancreatic islet β-cells and inhibit the secretion of glucagon by pancreatic α-cells." (PMID 38762508, 2024). "In-depth studies looking into hormonal content within the pancreas in diabetics have reported findings of the reduction of insulin stores in the pancreas and glucagon stores that remained unchanged." (PMID 38665134, 2024).
diabetes (continued). "Investigating the urinary fate of AAs after a glucagon infusion improves our understanding of AA metabolism in hyperglucagonemic states, such as many forms of diabetes." (PMID 38814331, 2024). "α-cells, especially those secreting glucagon, have the capacity to spontaneously transform into insulin-producing cells, thereby aiding in diabetes recovery, particularly post-puberty." (PMID 39057094, 2024). "Typical glucagonoma syndrome includes diabetes, necrolytic migratory erythema, depression, and deep vein thrombosis in the presence of hypoaminoacidemia and high glucagon levels, usually > 1000pg/ml." (PMID 39309109, 2024). "GLP-1 peptide increases and decreases insulin and glucagon secretion, respectively, and modulates blood glucose levels and also one of the therapeutic targets for type 2 diabetes mellitus are GLP-1RAs (GLP-1 receptor agonists)." (PMID 38807723, 2024). "In fact, inhibition of glucagon action has previously been shown to ameliorate glucose control in diabetes." (PMID 39429740, 2024). "We developed a small molecule agonist of the EphA4 receptor to target suppression of glucagon secretion in α cells as a treatment of hyperglucagonemia-hyperglycemia in diabetes." (PMID 38258903, 2024). "Early results of clinical trials of co-agonists of glucagon and its related receptors (GLP-1R and glucose-dependent insulinotropic peptide receptor) as treatments for MASLD are promising (American Diabetes Association 2023, Boehringer Ingelheim 2024)." (PMID 38579751, 2024). "On the other hand, when insulin levels remain stable in diabetes patients, an increase in glucagon leads to hyperglycaemia and glycosuria." (PMID 38579770, 2024). "The incident diabetes group had increasing plasma glucose, decreasing glycine and elevated insulin and glucagon levels." (PMID 39078488, 2024). "Insulin and glucagon levels were lower in the type 1 diabetes group compared with the type 2 diabetes group, and similar to those in the non-diabetes group." (PMID 39078488, 2024). "One interesting aspect related to glucagon's role in enhancing insulin action is the development of the bionic pancreas, which combines glucagon and insulin to prevent hypoglycaemic episodes in people with diabetes." (PMID 38579770, 2024). "Some researchers argue that excessive glucagon expression may play a more crucial role in diabetes development than insulin deficiency, as accumulation of glucagon could potentially play a more important role in the progression of diabetes compared to insufficient insulin production." (PMID 39641365, 2024). "The rapid and pulsatile interplay of glucagon and insulin in the fasting state has been elaborated by Nauck and Meier in healthy people and in prediabetes or diabetes." (PMID 38579770, 2024). "Elevated fasting glucagon levels (hyperglucagonemia) are present in obese individuals with (pre-)diabetes and are predictive of future diabetes development." (PMID 39114126, 2024). "Fasting levels of glucagon are known to be elevated in youth and adults with type 2 diabetes mellitus (T2D)." (PMID 39027470, 2024). "Our study indicates a potential role of adropin in modulating glucagon secretion in animal models of diabetes mellitus." (PMID 39337311, 2024). "Previous studies have shown that PDX-1 and NeuroD1 are affected in genotypic animal models of diabetes, and there is also an increase in glucagon and alpha cells in pancreatic islets." (PMID 38745946, 2024). "have described how hyperglycemia in healthy individuals results in a suppression of glucagon to subnormal levels, while this effect is dramatically attenuated in individuals with diabetes mellitus." (PMID 39027470, 2024). "Its role in diabetes treatment is significant, as it induces insulin secretion, suppresses glucagon secretion, slows down gastric emptying, and decreases appetite and food intake." (PMID 39220011, 2024).
diabetes (continued). "Historically, research on glucagon within the context of diabetes has predominantly focused on its counterregulatory effects on insulin." (PMID 38477666, 2024). "Generally, little is known about the effect of adropin on α-cells and glucagon secretion in diabetes mellitus." (PMID 39337311, 2024). "The analysis indicated alteration of many metabolic pathways related to diabetes, such as insulin and glucagon signaling pathways and regulation of lipolysis in adipocytes." (PMID 38880916, 2024). "All children and adolescents with diabetes should be prescribed intranasal or subcutaneous glucagon." (PMID 38894740, 2024). "DPP4i manages diabetes by stimulating insulin secretion and inhibiting glucagon secretion through elevating endogenous GLP-1 levels." (PMID 38405664, 2024). "It has shown efficacy in glucose control for diabetes mellitus type 2 patients by increasing insulin secretion, lowering glucagon release, and slowing gastric emptying." (PMID 38975533, 2024). "Further research is needed to better understand glucagon’s role in alpha cell dysfunction in diabetes." (PMID 39594662, 2024). "GLP-1 also inhibits glucagon secretion, which is also helpful in treating diabetes because glucagon is the hormone that promotes the release of blood glucose in the body in a fasting state." (PMID 39834977, 2024). "In conclusion, this study was the first to assess the clearance and reduction rates of insulin and glucagon in patients with diabetes undergoing HD." (PMID 37445782, 2023). "This review compiles recent evidence for the role of SST receptor 2 (SSTR2) signaling in the pathophysiology of glucagon counterregulatory failure in diabetes." (PMID 38298268, 2023). "Amylin secretion is diminished in patients with diabetes which involved in the suppression of endogenous glucagon production,reduces postprandial hepatic glucose production and induces satiety." (PMID 37808382, 2023). "Diabetes is characterized as a bi-hormonal disorder, owing to the defective secretion of both glucoregulatory hormones, insulin and glucagon." (PMID 38298268, 2023). "Also, glucagon may add to the risk of developing diabetes in such patients." (PMID 37425212, 2023). "In diabetes, dysregulated glucagon response induces excessive hepatic glucose output, contributing to fasting hyperglycemia." (PMID 37513589, 2023). "Selective antagonism of SSTR2 has been shown in various non-clinical models of T1D and in early phase clinical trials to at least partially restore glucagon counterregulation, with the goal of reducing hypoglycemia exposure in insulin-requiring diabetes." (PMID 38298268, 2023). "The magnitude of hyperglucagonemia and reduction of Gcgr expression obtained in the inducible adult αRhebTg mice is more aligned to glucagon levels in pathological states such as diabetes." (PMID 37140984, 2023). "(2019) delve into the dysregulated glucagon secretion and its implications for diabetes, showcasing how specific lncRNAs, such as Paupar, play a vital role in α-cell development and function, providing a distinct mechanism for glucose homeostasis." (PMID 38027148, 2023). "This secretory pattern becomes defective in diabetes and leads to glycaemic volatility: failure to secrete glucagon at low glucose contributes to the occurrence of hypoglycaemia, while hyperglucagonemia at high glucose exacerbates hyperglycaemia." (PMID 37159865, 2023). "GLP1 receptors are present in many tissues, but with regards to the therapeutic effects on diabetes, their activation is thought to increase insulin secretion, and reduce beta cell apoptosis and glucagon release in a glucose-dependent way." (PMID 37242585, 2023). "Dysregulation of glucagon is also responsible for worsening diabetes, and it has been reported that in insulin-resistant α-cell lines, there is a disturbance in the regulation of glucagon secretion and expression." (PMID 37626767, 2023).
diabetes (continued). "This study supports the notion that glucagon and inhibition of glucagon receptor signaling can be used as a strategy to control hyperglycemia in diabetes." (PMID 37140984, 2023). "Finding novel and effective suppression of hepatic glucagon response antidiabetic compounds is urgently required for the development of new drugs against diabetes." (PMID 36937284, 2023). "At the same time, these findings are important considering the current clinical trials exploring the use of dual insulin/glucagon pumps for the treatment of diabetes." (PMID 37140984, 2023). "Of them, DPP-4is universally increase insulin secretion, and decrease levels of intact glucagon in patients with diabetes via potentiation of GLP-1 action." (PMID 38189048, 2023). "We believe these findings are critical to interpreting the temporal changes in glucose homeostasis after increases in glucagon in diabetes." (PMID 37140984, 2023). "Diabetes mellitus (DM) is a group of physiological abnormalities characterized by hyperglycemia caused by insulin resistance, insufficient insulin production, or overproduction of glucagon." (PMID 37978526, 2023). "In conclusion, GLS2 impairment in pancreatic β-cells induces insulin impairment and paradoxical glucagon increase, resulting in diabetes mellitus." (PMID 37147373, 2023). "We provided new insights into the cellular basis for CGA in the regulation of glucagon-induced hepatic gluconeogenesis in diabetes." (PMID 37513589, 2023). "Short hairpin RNA–mediated (shRNA-mediated) suppression of HNF1A in primary human pseudoislets led to blunted insulin output and dysregulated glucagon secretion after transplantation in mice, recapitulating phenotypes observed in patients with diabetes." (PMID 37943614, 2023). "This study also suggested that reduced serotonergic control of α-cells can be a contributing factor for glucagon dysregulation in diabetes." (PMID 37159865, 2023). "This suggests that disordered BCAA catabolism in pancreatic islet cells contributes to the postprandial hypersecretion of glucagon in diabetes." (PMID 37764697, 2023). "Due to these actions on insulin and glucose, suppression of glucagon action was initially considered a good strategy to treat diabetes." (PMID 36943057, 2023). "Patients with type 2 diabetes mellitus (T2DM) exhibit high plasma glucagon levels in the fasting periods and lack the ability to inhibit its secretion after a meal." (PMID 37635984, 2023). "We also discuss α-cell pathophysiology and the perspective of addressing glucagon secretory defects in diabetes for developing better diabetes treatment, which bears the hope of eliminating hypoglycaemia as a clinical problem in diabetes care." (PMID 37159865, 2023). "The pancreas is mainly used to treat diabetes, and its main function is to stimulate pancreatic secretion and inhibit the release of glucagon." (PMID 36873938, 2023). "The role of glucagon dysregulation in diabetes is recognised, and glucagon receptor antagonists are already emerging as a promising new class of anti-diabetic drugs." (PMID 37159865, 2023). "That would be of great value since glucagon secretion and action and their role in the pathogenesis of diabetes have been understudied, compared to insulin, also due to the lack of appropriate methodologies to accurately assess them." (PMID 37030857, 2023). "This review also summarizes the non-clinical and clinical data available to date on SSTR2 antagonism as a therapeutic approach to restoring glucagon counterregulation in diabetes." (PMID 38298268, 2023). "This relationship has been reinforced by recent findings that glucagon/GLP-1 receptor dual agonists lead to improved blood glucose in type 2 diabetes mellitus (T2DM) patients." (PMID 37635984, 2023). "Inspection of the same counts among the diabetes‐treated groups, however, indicates that the fold increase of insulin+ cells is higher than the fold increase of glucagon+ cells." (PMID 36647783, 2023).
diabetes (continued). "The glucagon cell ratio of the diabetes group was higher than the control group (p < 0.001) and the glucagon cell ratio of the GQD group was significantly increased compared to the diabetes group (P < 0.01)." (PMID 35858880, 2022). "In patients with diabetes, levels of glucagon are elevated during fasting and, in response to carbohydrate ingestion, the normal suppression is delayed or even briefly reversed." (PMID 34713962, 2022). "Since trafficking to the Lamp2A+ lysosome is inhibited in diabetes, it is possible that glucagon is trafficked to a secretory lysosome." (PMID 34923907, 2022). "In the diabetes group, the islets were in irregular shape and the glucagon positive cells were randomly distributed in the islet residue (dotted line)." (PMID 35858880, 2022). "In diabetes, glucagon secretion from the pancreatic α-cell becomes abnormally up-regulated, resulting in hyperglucagonemia." (PMID 34923907, 2022). "We envision that the method describe in this study will pave the way for monitoring of glucagon levels in individuals with diabetes." (PMID 35590248, 2022). "Concerted studies of insulin and glucagon are necessary to understand the effects of dietary modifications on obesity and diabetes." (PMID 36056607, 2022). "The number of glucagon-positive cells continue to increase after 1 and 2 weeks of diabetes mellitus." (PMID 35563364, 2022). "Declines in either plasma insulin or the sensitivity to insulin in diabetes would be expected to lift its inhibition of cAMP‐mediated responses to glucagon." (PMID 35569125, 2022). "But in the third, the suppressed basal AC activity was observed ex vivo after diabetes had produced a marked increase in plasma glucagon levels in vivo (103 pM from 28 pM)." (PMID 35569125, 2022). "Ranolazine lowers the levels of glycated hemoglobin and fasting blood glucose, and it inhibits the release of glucagon in diabetic patients, which has a positive effect on the treatment of diabetes." (PMID 35155576, 2022). "For example, plasma glucagon concentrations increase during SGLT2 inhibitor therapy for diabetes, contributing, at least in part to the three- to fourfold increased risk of ketoacidosis in these individuals." (PMID 35590248, 2022). "In this review, recent research on the mechanisms by which glucagon and its receptor contribute to the pathogenesis of diabetes as well as correlations between GCGR mutation rates in populations and the occurrence of diabetes are summarized." (PMID 35784565, 2022). "Units sold per person from 2014 to 2021 were 0.407 ± 0.661 to 0.507 ± 0.774 (Mean ± SD) in 2021, that means that < 50% of persons with diabetes had glucagon available, and probably even fewer persons were treated with glucagon for SH." (PMID 36550552, 2022). "The glucagon level and fasting serum insulin were evaluated in all groups after 12-week diabetes treatment and induction." (PMID 35211170, 2022). "Glucagon is also involved in acutely regulating glucose homeostasis and administration of pharmacological doses of glucagon in animal models for diabetes or obesity has demonstrated regulatory effects on lipid metabolism, energy expenditure, and food intake." (PMID 36313764, 2022). "The clinical focus of gluconeogenic regulators, glucagon and GCGR, predominantly centers on diabetes, whereby unabated glucagon signaling, due to insulin resistance, contributes to hyperglycemia." (PMID 35123542, 2022). "According to the theory of bihormonal regulation, diabetes results from the abnormal secretion of both insulin and glucagon." (PMID 35784565, 2022). "In the present study, we show that in STZ-induced diabetes in male mice, the abnormally high secretion of glucagon is accompanied by a relative decrease in cellular Stmn2." (PMID 34923907, 2022). "Given the increasing appreciation of glucagon’s central role in the etiology of diabetes, resolving persistent uncertainties and establishing its true mechanism of action in health and disease are now more urgent than ever." (PMID 35569125, 2022).